TRIB3 (tribbles pseudokinase 3)
Diseases named in the same sentence as TRIB3 in open-access papers (continued):
Sharing a sentence is not in itself a finding about the gene and the disease.
cancer (continued). "Given that TRIB3 is highly expressed in BC tissues, supports cancer stemness, and promotes tumor progression, inhibiting TRIB3 is suggested as a promising therapeutic strategy for BC." (PMID 39881875, 2024). "In our study, TRIB3 was mainly enriched in the cancer-related hallmarks of myc targets V2, mTOR1 signaling, glycolysis, hypoxia, DNA repair and unfolded protein response." (PMID 38006403, 2023). "At the same time, the stRNA-seq verified that TRIB3 was predominantly expressed in cancer tissues, further justifying its upregulated expression pattern in KIRC." (PMID 37153569, 2023). "In intestine cells, TRIB3 interacts with β-catenin and TCF4 to increase the expression of genes associated with cancer stem cells and promote CRC tumorigenesis." (PMID 35610288, 2022). "Previous studies have shown that TRIB3 expression is elevated in several types of cancer, and it promotes the migration of tumor cells through modulation of various oncoproteins." (PMID 35726370, 2022). "In cancer, TRIB3 increases stemness of cancer cells through activating transcription factors which induce expression of stemness-related genes." (PMID 36008442, 2022). "Among TRIB family, TRIB3 have been demonstrated to promote inflammation and cancer development by interacting with intracellular signaling molecules and proteins." (PMID 35473511, 2022). "Inhibition of protein SUMOylation induces autophagic-mediated cancer cell death through the upregulation of tribbles pseudokinase 3 (TRIB3) and inhibits cancer cell invasiveness through the activation of the small GTPase rac1." (PMID 35465332, 2022). "TRIB3 is a protein kinase that controls cell proliferation and differentiation and has been demonstrated to promote cancer development." (PMID 36463181, 2022). "A growing body of evidence suggests that TRIB3 is involved in the regulation of various biological processes that are relevant to cancers." (PMID 36555349, 2022). "Further, lidocaine induced apoptosis and apoptosis-inducible Tribbles homologue 3 (TRIB3) was also commonly upregulated in lidocaine-treated cancer cell lines." (PMID 36008442, 2022). "Inhibition of TRIB3 was described to enhance the tumorigenicity of several cancer cell lines by increasing AKT activity." (PMID 36295788, 2022). "Recent studies have found that TRIB3 is highly expressed in many tumors, including breast, lung, colorectal, and liver cancers, and it is closely related to tumor stage, recurrence, and prognosis." (PMID 35726370, 2022). "RNA-seq revealed that apoptosis-inducible TRIB3 was also significantly upregulated as a commonly modified gene in the examined cancer cell lines with lidocaine treatment." (PMID 36008442, 2022). "Intriguingly, elevated expression of TRIB3 was observed in tumor tissues in comparison with the para-carcinoma tissues." (PMID 35473511, 2022). "This review focuses on one particular Tribbles family member, namely, TRIB3, addressing its gene and protein expression, as well as its role in cancer development and progression." (PMID 33920424, 2021). "Some relevant studies have reported that TRIB3 played a key role in the anti-cancer activity of cannabinoids, and the gene inactivation of TRIB3 promoted the occurrence of cancer." (PMID 34957220, 2021). "These complex interactive functions of TRIB3 are encouraging to better understand the processes in which it is involved, but also to explore novel cancer therapeutic approaches that target TRIB3." (PMID 33920424, 2021). "In some cellular and animal models of cancer, TRIB3 repression or deletion leads to enhanced cell proliferation and tumor formation in xenograft models, suggesting a potential role as tumor suppressor for TRIB3." (PMID 33920424, 2021). "Taken together, these data indicate that in cancer, TRIB3 is upregulated both at mRNA and protein level." (PMID 33920424, 2021).
cancer (continued). "Previous work by different groups has shown that TRIB3 can exert both oncogenic and onco-suppressive functions in different cellular and animal models of cancer." (PMID 34771470, 2021). "In 2007, a study on the TRIB3 putative role in tumorigenesis, included the analysis of TRIB3 mRNA expression level in different carcinomas." (PMID 34198908, 2021). "Our data demonstrate that TRIB3 positively regulates the cancer stem-cell activity and in vivo tumorigenicity of EC cells by modulating β-catenin signaling through directly interacting with the ELF4 transcription factor." (PMID 33334065, 2020). "We also found that the expression of TRIB3 was increased in EC tumorspheres and that the knockdown of TRIB3 caused a reduction in the CSC marker ALDH1A1, as well as cancer stemness genes." (PMID 33334065, 2020). "The knockdown of TRIB3 in EC cells causes a reduction in cell proliferation, migration, invasion, CSC activity, and in vivo tumor formation through the inhibition of cancer stemness genes, such as BMI1, OCT4, Nanog, β-catenin, and c-MYC." (PMID 33334065, 2020). "We found that the messenger RNA (mRNA) expression level of TRIB3 was significantly and positively correlated with shorter overall survival of EC patients in The Cancer Genome Atlas database." (PMID 33334065, 2020). "TRIB3 is emerging as a potential therapeutic target for cancer because abrogating its expression dramatically reduces tumorigenesis and cancer progression." (PMID 33298911, 2020). "In particular, TRIB3 is upregulated in various cancer tissues and tightly related to the poor prognosis of patients, including non-small-cell lung cancer, breast cancer, and colorectal cancer." (PMID 33203798, 2020). "The inhibition of tumorsphere formation capability, epithelial–mesenchymal transition (EMT), cancer stemness genes, and tumorigenicity was observed in EC cells when TRIB3 was knocked down." (PMID 33334065, 2020). "TRIB3 has been demonstrated to reduce adipogenesis and insulin signaling, but its role in cancer development is controversial." (PMID 33334065, 2020). "The protein expression of TRIB3 was found to be significantly increased in EC cancer stem cells (CSCs) enriched by tumorsphere cultivation." (PMID 33334065, 2020). "TRIB3 is upregulated in various cancer tissues and is closely connected to the poor prognosis of patients." (PMID 33203798, 2020). "Knockdown of TRIB3 in EC cells suppressed tumorsphere formation, the expression of cancer stemness genes, and the in vivo tumorigenesis." (PMID 33334065, 2020). "The role of TRIB3 in malignant tumors is still controversial, and further work is needed to understand its role in ERS response pathway fully." (PMID 32160655, 2020). "In line with this notion, it has been recently reported that capsaicin promotes apoptosis in cancer cells via TRIB3 upregulation." (PMID 30987128, 2019). "Several anti-cancer agents that stimulate autophagy-dependent cell death produce their effects by upregulating Tribbles pseudokinase-3 (TRIB3), including natural compounds of lipid origin that exhibit structural similarities to GA." (PMID 31578236, 2019). "TRIB3 promotes chronic inflammation and cancer by interacting with intracellular signaling and functional proteins." (PMID 31844113, 2019). "Specifically, we found that inhibiting protein SUMOylation induces autophagic cell death through the upregulation of the pseudokinase TRIB3, and it impairs cancer cell invasiveness by inhibiting activation of the small GTPase RAC1." (PMID 31578236, 2019). "Previous studies have shown that administration of different anticancer agents induces cancer cell death via TRIB3 upregulation and subsequent inhibition of AKT activation." (PMID 30176898, 2018). "Overall, these data suggested that CA exerted anti-cancer effects via reduction of AKT by increasing CHOP/TRIB3 expression, besides CA induced ER-stress-CHOP dependent apoptosis." (PMID 30176898, 2018).
cancer (continued). "Recent studies reported that increase in TRIB3 expression promoted cancer cell death through apoptosis." (PMID 28105922, 2016). "This work provides the proof‐of‐concepts for targeting the TRIB3/SQSTM1 interaction as a therapeutic strategy against cancers, especially in T2D patients with cancers." (PMID 27038142, 2016). "TRIB3 depletion not only protects against the tumor‐promoting actions of insulin/IGF in cancer cells, but also suppresses tumor initiation, growth and metastasis in diabetic mice." (PMID 27038142, 2016). "Genetic inhibition of TRIB3 resulted in activation of mTORC2/AKT/FOXO pathway and was associated with more aggressive phenotype in several animal models of cancer." (PMID 28105922, 2016). "This is consistent with the data obtained in human concerning TRIB1 in blood T-cells, for TRIB2 in LT7 cancer cells and for TRIB3 in Muller cells." (PMID 24834131, 2014). "Additional Twist1 candidate target genes identified by microarray, Trib3 and Serpinb9b, promote proliferation of cancer cells and dendritic cells, respectively." (PMID 22242143, 2011). "Trib3 expression is increased in several primary tumours and cancer cell lines and can be controlled by nutrient starvation, which is consistent with these data." (PMID 19904274, 2009). "Quantitative real-time RT–PCR on 202 paired cancer and normal samples showed that 181 of 202 (89.6%) samples had higher levels of TRIB3 mRNA in cancerous regions than in normal regions." (PMID 19904274, 2009). "Notably, sorafenib alone, devoid of in vivo cancer environments, elicited a minimum threefold increase in TRIB3 expression, with a predominant localization of TRIB3 within the nucleus." (PMID 39932456, 2025). "The present research preliminarily explored whether TRIB3 may be viewed as a possible cancer biomarker, which provides a reference for the development of precision medical treatment (such as immunotherapy) of LSCC." (PMID 39869954, 2025). "However, ATF3, ATF5, PMAIP1, DDIT4 and CHOP, which are downstream genes of ATF4, were upregulated by Ocoxin in at least one of the studied cancers, while TRIB3 was overexpressed in all of them." (PMID 40176904, 2025). "TRIB3 can not only regulate cell proliferation, differentiation, cell cycle and cell death, but also modulate the cell cycle and physiological activities of cancer cells." (PMID 39869954, 2025). "The roles of LDH-5, HIF-1α, TRIB3, and hypoxia-related lncRNAs highlight the complex connections between cellular responses to low oxygen levels and cancer progression, underscoring the need for further investigation into these factors as potential therapeutic targets or prognostic indicators." (PMID 40322886, 2025). "ABTL0812 inhibits the AKT-mTORC1 axis via upregulation of TRIB3 in cancer cells and tumor models." (PMID 39544928, 2024). "Previous studies have demonstrated that TRIB3 was oncogenic across various cancer types, characterized by stemness formation, the impediment of autophagic and proteasomal degradation processes, and cancer immune evasion." (PMID 39362848, 2024). "Resultantly, TRIB3 acts as a determinant of cell fate in numerous cancer types." (PMID 38429254, 2024). "However, it failed to block the induction of ATF4, ATF3, CHOP, GADD34, and TRIB3 proteins induced by DT-061 treatment in cancer cells." (PMID 39349971, 2024). "Similarly, another study showcased TRIB3’s role in promoting the cancer stem cell (CSC)-like properties of cancer cells by inhibiting the β-TrCP-mediated ubiquitination degradation of TAZ (a key downstream molecule of the Hippo pathway)." (PMID 38137461, 2023). "The functions of TRIB3 on cancer progression have attracted multiple studies." (PMID 37732314, 2023). "The interaction of TRIB3 and the autophagic receptor P62 (Sequestosome 1) interferes with the degradation of autophagy and the ubiquitin–proteasome system to control the initiation and progression of cancer." (PMID 37042179, 2023).
cancer (continued). "The expression of TRIB3 in 21 malignant tumors was accessed using the TIMER2.0 database." (PMID 38235126, 2023). "Numerous types of tumors may share similar genetic or molecular features, there are a lot of studies showed that NUPR1 and TRIB3 are involved in cancer biology, and we think this prognosis model that includes these genes may be applied to more types of tumors." (PMID 37626099, 2023). "Moreover, the results of a mechanical analysis showed the relatively elevated chromatin accessibility of TRIB3 in tumor epithelial cells in the scATAC data, while stRNA-seq verified that TRIB3 was predominantly expressed in cancer tissues." (PMID 37153569, 2023). "These indicates that CHOP-induced GDF-15 and TRIB3 have significant roles in cancer." (PMID 36008442, 2022). "In addition, high TRIB3 expression correlates with advanced clinical stage and poor differentiation in many cancers." (PMID 35726370, 2022). "Moreover, TAZ displayed similar clinical significance and oncogenic functions as YAP1 did in EC and was responsible for tribbles pseudokinase 3 (TRIB3)-driven cancer stemness and radioresistance of ESCC." (PMID 36289774, 2022). "Inhibiting the expression of TRIB3 may significantly reduce the occurrence and progression of cancer." (PMID 35726370, 2022). "Collectively, these results suggest a role for TRIB3 in promoting cancer growth and indicate that TRIB3 may be a prognostic marker and/or therapeutic target." (PMID 35726370, 2022). "Knockout of TRIB3 inhibits tumorigenesis and cancer progression." (PMID 33841505, 2021). "In a recent publication from our group we demonstrated that the transcriptional co-repressor GCF2 (GC-Binding Factor 2) alias LRRFIP1 (Leucine Rich Repeat (In FLII) Interacting Protein 1) participates in TRIB3 downregulation in cancer cells incubated with rapamycin or its derivatives (rapalogs)." (PMID 33920424, 2021). "Among them, BST2, CALR, DDIT3, HSPA5, and TRIB3 were significantly up-regulated in cancer tissues." (PMID 34580365, 2021). "TRIB3 is also being investigated as a cancer biomarker and therapeutic target, especially in the context of its stress adjusting action that links homeostasis, metabolic disease and cancer." (PMID 33527138, 2021). "In addition, considerable number of studies suggest that TRIB3 dysregulation plays a role in cancer development, progression, and metastasis." (PMID 33920424, 2021). "We then state the contribution of TRIB3 to cancer development, progression, and metastasis." (PMID 33920424, 2021). "Similarly, emodin (present in Chinese medicinal herbs Rheum and Polygonum) and capsaicin (present in chili peppers) were shown to trigger NFkB/TRIB3-dependent autophagic cell death in different cancer cell types." (PMID 33499163, 2021). "Intriguingly, different studies have found that TRIB3 can exert both oncogenic and onco-suppressive actions in different cancer types, which suggest that the impact of TRIB3 dysregulation in tumorigenesis might be determined by the cellular context." (PMID 34771470, 2021). "TRIB3 can contribute to tumor progression via the attenuation of the major intracellular degradative process named autophagy that has a potential preventive role against early stage cancer." (PMID 33920424, 2021). "The Cancer Genome Atlas (TCGA) database of HNSCC patients was used to examine the expression of up-regulated genes, and CALR, HSPA5, and TRIB3 were found to be highly expressed relative to solid normal tissue in cancer and the survival rate was reduced in patients with high expression." (PMID 34580365, 2021). "However, the precise mechanisms that determine this dual role of TRIB3 in cancer remain to be understood." (PMID 34771470, 2021). "TRIB3 (Tbio), for example, shows correlation with metastasis in five cancer cohorts." (PMID 33205077, 2020). "Sp2 may play a role in promoting cancer by regulating TRIB3 protein, which may be a prognostic factor and a potential new therapeutic target for HCC." (PMID 32160655, 2020).
cancer (continued). "Thus, it is worth examining the expression of MYC-related E3 ligases when MYC expression is evaluated in TRIB3-depleted cancer cells." (PMID 33298911, 2020). "We speculate that Sp2 may play a role in promoting cancer by regulating the expression of TRIB3 protein." (PMID 32160655, 2020). "Previous studies have reported that TRIB3 is a potential target for cancer treatment." (PMID 32874132, 2020). "Sp2 may play a part in promoting cancer by regulating TRIB3 protein, which may be a factor of prognostic and a potential new therapeutic target for HCC." (PMID 32160655, 2020). "In this study, the role of Sp2 in promoting cancer may be related to the feedback effect of TRIB3 in ERS." (PMID 32160655, 2020). "Indeed, diminishing the formation of SUMO1 complexes induces autophagy-mediated cancer cell death through increasing the expression of Tribbles pseudokinase 3 (TRIB3)." (PMID 31578236, 2019). "Genes associated with the most common VELs included novel genes and several known oncogenes and tumour suppressors implicated in CRC as well as other forms of cancer, including MYC10, 16, BMP4 (refs 17, 18), PHLDA1 (refs 19, 20, 21, 22), SOX9 (refs 23, 24, 25) and TRIB3 (refs 26, 27)." (PMID 28169291, 2017). "Tribbles homolog 3 (TRIB3), a pseudokinase, plays an important role in cancer cells and adipocytes." (PMID 28871113, 2017). "The contribution of Tribbles isoforms in mammals to insulin regulation and cancer is complex: recently, TRIB2 has been shown to be an Akt agonist, and an R107L mutation in TRIB1 that aligns with R141Q in TRIB3 promotes leukemogenesis by enhancing ERK phosphorylation and C/EBPα degradation." (PMID 29025897, 2017). "Hence, their results further indicate that TRIB3 acts as a proto‐oncogene sustaining the cancer cells a feature of cancer‐initiating phenotype." (PMID 27038142, 2016). "However, the difficulty of cellular uptake has hindered A2 to exert its interrupting the TRIB3/SQSTM1 interaction in cancer cells." (PMID 27038142, 2016). "Thus, pharmacological agents that induce high TRIB3 levels should sensitize cancer cells to chemotherapy." (PMID 25121735, 2014). "Therefore, TRIB3 seems to function as a master ‘molecular switch’ for survival vs. death signaling in cancer cells undergoing ER-stress." (PMID 25121735, 2014). "TRIB3 is involved in regulating multiple pathways in cell survival and could thereby affect cell survival and cancer prognosis." (PMID 23185332, 2012). "Understanding TRIB3 protein regulation mechanisms in more detail could provide valuable information for means to regulate cancer cell survival." (PMID 23185332, 2012). "Furthermore, the involvement of TRIB3 in multiple important signaling pathways makes it an interesting target for cancer therapy." (PMID 21864376, 2011). "A total of 20 cancer cell lines (90.9%) expressed the TRIB3 gene." (PMID 19904274, 2009). "Although previous reports showed that TRIB3 is expressed in several cancer cell lines, this study shows that TRIB3 seems to stimulate proliferation, and may be a new target for the therapy of gastrointestinal cancer." (PMID 19904274, 2009). "Consequently, targeting TRIB3 to increase ferroptosis in HNSCC cells may effectively inhibit cancer progression." (PMID 38429254, 2024). "Additionally, our findings suggest a critical role of TRIB3 in the modulation of ferroptosis, where inhibiting TRIB3 activity potentiates the sensitivity of cancer cells to ferroptosis inducers, such as erastin, which is correlated with reduced ferrous iron and GSH levels." (PMID 39362848, 2024). "The subsequent analysis of TRIB3 demonstrated that this gene was positively associated with TNM staging of KIRC, implying its adverse role in the survival outcome of KIRC, which could be the leading contributor to the metastasis of cancer cells." (PMID 37153569, 2023).